MIR1302-4 (microRNA 1302-4)
Synonyms: hsa-mir-1302-4; MIRN1302-4
Gene: MicroRNA gene on chromosome 2 (207,269,275 to 207,269,424, reverse strand). Ensembl gene ENSG00000221628.
Gene Ontology:
Biological process: miRNA-mediated post-transcriptional gene silencing